RNU6-204P (RNA, U6 small nuclear 204, pseudogene)
Gene: Small nuclear RNA gene on chromosome 4 (3,044,101 to 3,044,207, forward strand). Ensembl gene ENSG00000199335.
Homologues: Orthologues: chimpanzee U6 (96% identical), macaque U6 (93% identical), rabbit U6 (84% identical), rabbit U6 (83% identical), dog U6 (69% identical), pig U6 (68% identical). Paralogues in human: RNU6-11P (87% identical), RNU6-1209P (87% identical), RNU6-183P (87% identical), RNU6-268P (87% identical), RNU6-37P (87% identical), RNU6-812P (87% identical), RNU6-1309P (86% identical), RNU6-16P (86% identical), RNU6-196P (86% identical), RNU6-35P (86% identical), RNU6-480P (86% identical), RNU6-1 (85% identical), and 1286 more.